PLAC8L1 (PLAC8 like 1)
Tractability: No criterion of Open Targets' tractability assessment is met for any kind of drug.
Gene: Protein-coding gene on chromosome 5 (146,084,313 to 146,105,577, reverse strand). Ensembl gene ENSG00000173261.
Subcellular location (Human Protein Atlas): Nucleoplasm
Genetic constraint (gnomAD): Loss-of-function variants: 14 observed, 19.34 expected, observed/expected ratio (o/e) 0.72, 90% interval 0.48 to 1.13. The upper end of that interval is the gene's LOEUF score, 1.13, which puts it in group 4 of 6, group 1 being the genes least tolerant of losing a copy. Missense variants: 181 observed, 231.46 expected, observed/expected ratio (o/e) 0.78, 90% interval 0.69 to 0.88. Synonymous variants: 77 observed, 83.87 expected, observed/expected ratio (o/e) 0.92, 90% interval 0.76 to 1.11.
Homologues: Orthologues: chimpanzee PLAC8L1 (98% identical), macaque PLAC8L1 (95% identical), pig PLAC8L1 (81% identical), rabbit PLAC8L1 (81% identical), guinea pig PLAC8L1 (81% identical), rat Plac8l1 (81% identical), mouse Plac8l1 (77% identical), dog PLAC8L1 (76% identical), zebrafish plac8l1 (36% identical). Paralogues in human: CNFN (25% identical), PLAC8 (23% identical).
Diseases named in the same sentence as PLAC8L1 in open-access papers:
PLAC8L1 is named in the same sentence as 2 diseases in open-access papers, as found by Europe PMC text mining. Sharing a sentence is not in itself a finding about the gene and the disease. The quoted sentences say what the papers report.
breast carcinoma (1 paper, 2020). "Constitutional genes with increased breast cancer relapse risk were claudin 15, WDFY2, golgin A4, DOCK4 while HCG27 and PLAC8L1 were among 18 signature signs not endorsed by prognostic index score." (PMID 33106505, 2020).
PLAC8L1 also shares sentences with these, for which no sentence is quoted: genetic disease (1 paper).